CCR4 (C-C motif chemokine receptor 4)
Diseases named in the same sentence as CCR4 in open-access papers (continued):
Sharing a sentence is not in itself a finding about the gene and the disease.
tumor (continued). "In addition, the expression of CCR4, MX2, and NR3C2 were significantly correlated with the stromal score, immune score, ESTTIMATE score, and tumor purity." (PMID 35619698, 2022). "When compared to healthy donors, CCR4 expression is significantly increased by Tregs during tumor condition; however, CCR4 expression is not significantly increased by other T-cell subsets." (PMID 35222362, 2022). "In addition, the combination treatment of another CCR4 antagonist piperidinyl-azetidines and immune checkpoint inhibitors, such as anti-PD-L1 and CTLA-4 antibodies, efficiently augmented tumor-specific immune responses." (PMID 34885241, 2021). "Another plausible explanation for the impairment of clinical responses to mogamulizumab in advanced or recurrent solid (CCR4-negative) tumor patients is that mogamulizumab did not sufficiently deplete eTreg cells in the TME." (PMID 34907192, 2021). "CCR4 is expressed predominantly by effector Tregs, which are the most abundant cell type among FOXP3+ T cells in tumor tissue; in addition, CCR4 ligands produced by cancer cells or by infiltrating macrophages appear to be involved in migration and infiltration of Tregs into various tumor tissues." (PMID 34445615, 2021). "CCR8 and P2RY14 were significantly differentially expressed in tumor tissues compared with normal tissues, while CCR4 was not significantly different." (PMID 33692955, 2021). "Therefore, this study generated Msln-CAR T cells modified with CCR2b or CCR4, and findings showed that Msln-CCR2b-CAR and Msln-CCR4-CAR T cells increased migration to tumor supernatants with a high level of Mcp-1 in vitro." (PMID 33777013, 2021). "Therefore, blocking the functional molecules expressed on Tregs such as CTLA-4, PD-1, CCR4, TGF-β, Foxp3, or completely eliminating the presence of Tregs can improve the immune escape effect of tumor inflammatory microenvironment." (PMID 34062992, 2021). "These interesting findings could encourage the evaluation of an association of proton therapy with for example an anti-CTLA4 or an anti-CCR4, which, by targeting Tregs, induce reactivation of CD8+ T cells against tumor cells." (PMID 34188135, 2021). "These cells preferentially express CCR4 (believed to have a major role in the recruitment of Tregs to the TME), which is being targeted with an anti-CCR4 monoclonal antibody, mogamulizumab, in different tumor types, including HNSCC." (PMID 33718169, 2021). "CCL22 is produced by macrophages, dendritic cells and tumor cells and is a chemoattractant for several cell types including regulatory T cells and T helper type 2 cells, as evidenced by their expression of the CCL22 receptor, CCR4." (PMID 33202734, 2020). "To further clarify the mechanism underlying the functions of the four previously discovered key genes (CCR2, CCR4, P2RY12, and P2RY13) in the tumor microenvironment, we divided LUAD patients into high-expression groups and low-expression groups according to the four gene expression levels." (PMID 33318300, 2020). "The expression of CCR4 was significantly correlated with the infiltration levels of eosinophils, macrophages M0, and CD8+ T cells (which illustrates the relationships between the expression of CCR4 and tumor-infiltrating immune cells)." (PMID 33181717, 2020). "It was then no coincidence that anti-CCR4 treatment in patients with adult T-cell leukemia-lymphoma evoked strong tumor antigen-specific CD8+ T-cell response." (PMID 33375291, 2020). "Similarly, the co-expression of CCR2 and CCR4 in CAR T cells has been shown to improve homing to the tumor site and anti-tumor function in mouse models of malignant pleural mesotheliomas, Hodgkin’s lymphoma and neuroblastoma, respectively." (PMID 32570906, 2020). "Since CCL22 attracts CCR4+ lymphocytes, such as CTCL cells, Tregs, and Th2 cells, the decrease in CCL22 might suppress the development of tumor mass in vivo." (PMID 31616630, 2019).
tumor (continued). "Furthermore CCR4 (receptor for CCL17 and CCL22) antagonists have been shown to decrease the tumor-promoting environment." (PMID 30850664, 2019). "Together, our data establish a critical role for Not3 and the entire CCR4-NOT complex as tumor suppressor." (PMID 30144809, 2018). "In the tumor microenvironment, a high expression of CCL17/TARC and CCR4 by MCC cells may contribute to the activation of inflammatory pathways and the promotion of tumor growth and immune suppression." (PMID 30140381, 2018). "In contrast, when L428 was used in conjunction with an anti-CCR4 antibody, no tumor suppression was seen." (PMID 29222435, 2017). "In view of significant correlation between expression level of CCR4 and clinical invasive characteristics in HCC patients, CCR4 might play a positive role in HCC tumor metastasis." (PMID 28959024, 2017). "Previous studies have shown that CCR4+ T cells can be recruited to the GBM microenvironment (Ti-CCR4+ T cells), and our data further indicated that CD4+CCR4+ T cells were relatively specifically enriched in GBM and more abundant in the tumor microenvironment than those in the peripheral blood." (PMID 29312296, 2017). "And we also found a remarkable correlation between the expression of CCR4 and tumor TNM stage, vascular invasion indicating that HCC cells expressed high level of CCR4 might have more invasive phenotype." (PMID 28959024, 2017). "Whereas mice inoculated with control cells developed no tumors or very small ones, tumor load in mice inoculated with CCR4 over-expressing (CCR4hi) cells was significantly higher." (PMID 28415693, 2017). "In conclusion, CCR4 could promote HCC malignancy, which can facilitate HCC tumor growth in vivo by neovascularization." (PMID 28959024, 2017). "We found that tumor-infiltrating CD4+CCR4+ T cells, but not CD4+CCR2+ T cells, were enriched in GBM tissues, suggesting that CD4+CCR4+ T cells had relatively specific infiltration in GBM." (PMID 29312296, 2017). "In addition, we determined that circulating aTreg cells, which highly express functional CCR4, migrated toward MCP-1 in the tumor microenvironment." (PMID 27177223, 2016). "Treg cells induction and recruitment to the local tumor tissue via CCR4/CCL22 signalling and tumor-derived TGF-β suggests that there is cross-talk between Treg cells and the tumor, which possibly leads to increased survival and malignancy of the tumor." (PMID 26020249, 2015). "Moreover, the authors have shown that tumor Tregs express functional CCR4, the receptor for CCL22, and can migrate to CCL22, present in the tumor microenvironment." (PMID 25647263, 2015). "Further studies should elucidate the tissue- or tumor cell-specific function of the CCR4-NOT complex." (PMID 26437789, 2015). "In addition, we also measured the expression of CCR4, CCR5 and CXCR3 receptors on tumor infiltrating CD8+ and CD4+ T cells from both WT and KO mice and found AMPK deficiency had no overt impact on the expression of these major chemokine receptors." (PMID 25760243, 2015). "In fact, in the absence of CCR4(+) Tregs, CCR4(+) tumor cells disseminated into the lung are efficiently eliminated by NK cells, because CCR4(+) Tregs directly kill NK cells using beta-galactoside-binding protein." (PMID 25110692, 2014). "Therefore, the balance of infiltrating CCR4(+) Tregs and CD8(+) T cells in tumor tends to be a seesaw." (PMID 25110692, 2014). "All tumor cells, monocytes/macrophages, and mDCs produce CCL22 to recruit Tregs via the GPCR CCR4." (PMID 25110692, 2014). "In addition, the generated anti-CCR4 antibodies possessed strong ADCC activity against CCR4+ cells and some tumor cell killing via phagocytosis." (PMID 25080123, 2014). "While their differential expression is yet to be assigned to either iTreg or nTregs cells, CCR4, PD-1, and CTLA-4, which have been shown to be highly expressed on tumor-Treg cells offer potential targets for treatment of cancers enriched in Treg cells with such phenotype." (PMID 23874336, 2013).
tumor (continued). "The chemokine receptors, CCR10 and CCR4, known to respond to chemo-attractants CCL27, MCP-1, and CCL22, have been shown to be critical in inducing mobilization and homing of myeloid cells and leukocytes to the tumor site." (PMID 23372791, 2013). "Furthermore, in CCR4+ tumor-bearing mice co-treated with AAV8-h1567 minibody and infused with human peripheral blood mononuclear cells (PBMCs), marked tumor infiltration of human CD16A+ CD56+ NK cells was observed." (PMID 22973452, 2012). "We infer this may result from the strong expression of CCL20 in tumor environment, which inversely internalizes the CCR6 expression like CCR4." (PMID 21935436, 2011). "Reduced efficacy in tumor-stage MF may partly be attributed to absent CCR4 expression in certain patients, as illustrated by patient 12 in the Kallinich study." (PMID 40861461, 2025). "Although the interaction between CCL22 and its receptor CCR4 may recruit regulatory T cells (Tregs) into the TME, thereby bolstering tumor immune evasion, it also fosters the infiltration of anticancer tumor-infiltrating lymphocytes (TILs), presenting a dual effect." (PMID 39512767, 2024). "Overall, the addition of MDMs to T cell-tumor cell co-cultures induced proinflammatory factors such as TNF secretion, elevated CTLA4 mRNA expression which is known to increase in response to T cell activation and simultaneously decreased anti-inflammatory CCR4 and TGFB1 mRNA expression." (PMID 39414902, 2024). "Previous findings of the present authors showed that CCL22 and CCR4 mRNA levels were higher in CC tissues compared with para-carcinoma tissue and normal cervix, and overexpression of CCL22 and CCR4 mRNA attributed immune disequilibrium in tumor microenvironment and promoted carcinogenesis." (PMID 39513112, 2024). "Consequently, MOG primarily operates by potently triggering ADCC against CCR4-positive tumor cells, with no observed evidence of CDC or direct cell death." (PMID 38396877, 2024). "Additionally, immune checkpoint molecules (e.g., CCR4, CD27, CD274, CD68, CTLA4, PDCD1, and PDCD1LG2) were significantly upregulated in the AERShigh group (all p < 0.01), suggesting potential impairment of the anti-tumor immune response." (PMID 39464883, 2024). "Moreover, the combination therapy increased the proportion of CD8+T cells in TME regardless of tumor response, indicating the potential of CCR4 targeting therapy." (PMID 38250084, 2023). "CC chemokine receptor 4 (CCR4), with two ligands, CCL17 and CCL22, is a key chemokine receptor selectively expressed on normal T cells that mediates the entry of regulatory T cells into the tumor microenvironment, and it is mainly expressed in tumor-infiltrated Treg cells." (PMID 36992198, 2023). "To further confirm the in vivo relevance of CCR4 signaling on NI in the herein described TPAC model, we treated TPAC mice (aged 42 weeks) with the CCR4 inhibitor C021 3 times a week for 3 weeks and subsequently analyzed the severity of NI in the primary tumor via histology." (PMID 37607005, 2023). "Although it remains elusive, it is tempting to assume that the frequent aggregation of RPB1 in tumor cells resistant to the transcription inhibitor epirubicin may be a consequence of a failure in the CCR4–NOT-dependent co-translational folding of RPB1." (PMID 37958852, 2023). "Remarkably, CCR4 expression was increased in Foxp3UP CD8 T cells, and in transwell assays these cells exhibited enhanced migration toward CCL22, which suggests that the CCL22/CCR4 axis may play a role in their tumor recruitment." (PMID 36045586, 2023). "Furthermore, Treg accumulation in GBM may be due to the interaction of CCR4, which is highly expressed on Tregs, and CCL22, which is a CCR4 ligand secreted by GBM tumor cells." (PMID 36768342, 2023). "Moreover, there was no statistical difference in tumor sizes between the CCR4 antagonist and the combination groups after the cessation of treatment for 3 weeks." (PMID 35177591, 2022).
tumor (continued). "In our study, the previously observed co-expression of CCR4 and CLA raises the possibility that this subset of Tregs migrate into the skin where they accumulate over years and dampen immune surveillance and contribute to tumor escape, hence subsequent cuSCC development." (PMID 34796183, 2021). "For example, since CCR4 is expressed not only on CTCL cells but also on regulatory T-cells, mogamulizumab might enhance the anti-tumor immune response at the tumor site, and it might be suitable for combination with local immunotherapies such as topical bexarotene or imiquimod." (PMID 33540765, 2021). "Analysis of the total thymic cell population suggests insignificant changes in CCL17 (ligand for CCR4) and a modest decrease in CCL19 (ligands for CCR7) at day 25 but a drastic reduction in expression of CCL21 (ligands for CCR7) when comparing thymi harvested from tumor-bearing vs. control mice." (PMID 32582141, 2020). "For this reason, small molecule antagonists of CCR4 with less harmful side effects are in development and one of them, AF399/420/1802, considerably improved the efficacy of cancer vaccines in different preclinical tumor models (melanoma, lung, and colon cancer) by preventing Tregs induction." (PMID 30894861, 2019). "However, contrary to the tumour suppressive function components of the CCR4-NOT complex, it can have an impact on cancer progression." (PMID 31572192, 2019). "In solid tumors, recent reports show that CNOT3 and other CCR4-NOT subunits could be involved in tumor formation/progression." (PMID 30144809, 2018). "Interestingly, and in agreement with sequencing data in human cancers, we also observed increased tumor formation upon knockdown of other members of the CCR4-NOT complex, including the deadenylases." (PMID 30144809, 2018). "Downregulation of other subunits of the CCR4-NOT complex also enhanced tumor formation." (PMID 30144809, 2018). "The results indicated that the CCR4 antagonist did not have a significant effect on tumor volume." (PMID 28415693, 2017). "CCR2+ T cells were nearly absent in FoxP3+CD4+ T cell fractions, indicating that HNSCC-circulating aTreg cells may be recruited to the tumor microenvironment by endogenous MCP-1 via binding to CCR4 but not CCR2." (PMID 27177223, 2016). "We therefore selected Cnot8 and its highly conserved paralog Cnot7 to determine whether the deadenylation function of CCR4-NOT plays a critical role in tumor progression." (PMID 26807845, 2016). "For example, mAbs targeting CCR4, a chemokine receptor heavily involved in Treg recruitment to the TME, have shown promising results in clinical and laboratory studies, effectively depleting activated FoxP3+CCR4+ Tregs with only a limited impact on tumor-infiltrating Teff and CTL subsets." (PMID 27509527, 2016). "The humanized defucosylated antibody to CCR4 (KW-0761, Phase II), was demonstrated to have antitumor activity in cutaneous T lymphoma and T-cell acute lymphoblastic leukaemia since the blockade of this receptor showed increased number of CD56 NK cells in the tumour microenvironment." (PMID 26062132, 2015). "Ligands for CCR4 (e.g., CCL17 and/or CCL22) were in contrast to IL-6 and TGF-β not highly expressed in the tumor tissue, altogether indicating a conversion from CD8+ Tconvs rather than a tumor directed migration as the cause for the observed infiltration." (PMID 24212779, 2011). "However, one case of tumor-stage MF entirely lacked CCR4 expression." (PMID 40861461, 2025). "Notably, chemokine receptors, including C-C chemokine receptor type 2, 4, 5, 6, 8, 10 (CCR2, CCR4, CCR5, CCR6, CCR8, CCR10), and C-X-C chemokine receptor type 3, 4 (CXCR3, CXCR4) have been identified as significant factors in the recruitment of Treg cells to the tumor site." (PMID 39000453, 2024). "However, CD8+ T cells, which do not express CCR4, are not attracted to the tumour." (PMID 39596267, 2024).
tumor (continued). "Mechanistically, IGF2BP3 maintains NOTCH3 mRNA stability via suppression of CCR4-NOT complex-mediated deadenylation in an m6A-dependent manner, which sustains Notch3 signaling activation and increases the transcription of stemness-associated downstream genes, eventually promoting tumor metastasis." (PMID 37853162, 2023). "Therefore, small molecule CCR4 antagonists might be a safer alternative to block Treg migration to the tumor microenvironment without Treg depletion." (PMID 33679808, 2021). "Furthermore, since CCR4 is also expressed by T regulatory (Tregs) cells, the authors speculate that anti-CCR4 CAR T cells would be able to eliminate Tregs cells which have typically an immunosuppressive role in the tumor microenvironment." (PMID 31058076, 2019). "In addition, it is well known that CCR4 is predominantly expressed by effector Treg cells, and Treg migration and infiltration into various tumor tissues are dependent on the expression of CCR4 ligands including CCL22 produced by tumor cells or infiltrating macrophages." (PMID 29383167, 2017). "Finally, we examined the presence of chemokines signaling through CCR4 and CXCR3 in protein extracts from tumor and unaffected tissue to investigate if differences in chemokine production could explain the altered T cell recruitment to tumor tissues." (PMID 22319577, 2012). "Unlike CCR4, which is also expressed on a subset of peripheral Tregs, CCR8 expression is highly restricted to immunosuppressive Tregs within the tumor microenvironment, making it an attractive candidate for selective targeting." (PMID 40672956, 2025). "CNOT2, as a core component of the CCR4–NOT complex, has emerged as a key modulator of gene expression programs that influence proliferation, apoptosis, and metabolic adaptation in tumor cells." (PMID 40864769, 2025). "Together, these findings reveal that the role of CCR4-NOT and P-bodies in HCC remains totally unclear, and thus, intense efforts are still required to generate conclusions about their tumor-promoting or tumor-suppressive functions." (PMID 39941720, 2025). "Our results demonstrate that C021, a class-I CCR4 antagonist, exerts multiple antitumor effects on CTCL cells in vitro and inhibits tumor growth in CTCL xenograft mice in vivo, whereas AZD-2098, a class-II CCR4 antagonist, does not show the same efficacy." (PMID 39302105, 2024). "Given that the CCR4-NOT complex functions as a non-specific deadenylase, we hypothesized that RNA binding partners recruit specific metastasis-associated transcripts for degradation, and variations in the efficiency of this process alter the metastatic capacity of tumor cells." (PMID 38410477, 2024). "CCR4+CCR6+ TAM were found to be significantly reduced after nCIT, while the percentage of total macrophages in the tumor microenvironment was not changed." (PMID 39703499, 2024). "Unlike CCR4, the target of mogamulizumab, CCR8 was selectively expressed on tumor Tregs and minimally expressed on effector T cells." (PMID 36765704, 2023). "Notably, since CCR4 expresses not only CTCL cells, but also skin‐homing T cells including CD8+ T cells and regulatory T cells (Tregs), bexarotene might modulate the profiles of tumour‐infiltrating lymphocytes (TILs) to induce an anti‐CTCL immune response in CTCL patients." (PMID 37275413, 2023). "Given that CCR4 deficiency does not affect the infiltration and migration of monocytes, CCR4 inhibition to block the CCL2/CCR4 axis could be a promising novel antitumoral strategy to reduce the risk of rapid tumor recurrence and metastasis during the cessation of CCL2 inhibition treatment." (PMID 35177591, 2022). "The immunophenotype of typical ATLL tumor cells is positive for CD3, CD4, CD5, CD25, CCR4, and CADM1, and negative for CD7 and CD8." (PMID 35625999, 2022). "For example, the forced expression of CCR4, which is absent on effector CD8+ T cells, increases both CAR T cell tumor infiltration and responses in small animal models with Hodgkin lymphoma." (PMID 34771608, 2021).